DES (desmin)
Diseases named in the same sentence as DES in open-access papers (continued):
Sharing a sentence is not in itself a finding about the gene and the disease.
tumor (continued). "The tumor cells were positive for smooth muscle actin (SMA), and negative for desmin, h-caldesmon, CD34, cytokeratin, S100 protein, and CD117." (PMID 23742153, 2013). "Immunohistochemistry the tumor was positive for vimentin, focal positivity with AE1-AE3 CK, CK5 and high molecular weight cytokeratin and negative for EMA, CD34, desmin, myosin, CroA, synaptophysin and S100." (PMID 23886403, 2013). "In our case, the tumor cells were positive for vimentin and SMA and negative for desmin and cytokeratin." (PMID 23936706, 2013). "Immunohistochemically, the tumour cells were positive for chromogranin and CD56, focal positive for S100, and negative for desmin, CD68, actin, SMA, and AE1/AE3." (PMID 22792486, 2012). "Immunohistochemically, tumor cells were positive for SMA, HMB45, and Melan-A and negative for CD10, RCC, CD45, CD117, CD34, EMA, and Desmin." (PMID 22953133, 2012). "The tumor cells were negative for CD34, CK 5/6, CK7, CK20, S100, desmin, α–SMA, CD45, CD30, CD68 and HMB45." (PMID 22943673, 2012). "Immunohistochemically, the tumor cells were widely positive for vimentin, CD56, CD99 and focally positive for synaptophysin, CD10, progesterone receptor, desmin and CD34, but negative for EMA, cytokeratin, estrogen receptor, S-100, GFAP and myoglobin." (PMID 23217062, 2012). "Immunohistochemically, the tumor cells were strongly positive for bcl-2 and CD99, partly positive for CK and EMA, and negative for CD117, CD34, SMA and desmin in all five cases." (PMID 22862905, 2012). "Immunostaining showed that the tumor was positive for the Vimentin, Bcl-2 and CD34, and was negative for S-100, desmin, CD68, and α–SMA." (PMID 23148444, 2012). "Immunohistochemically, the tumor cells were widely positive for vimentin, CD56, CD99 and focally positive for synaptophysin, CD10, progesterone receptor, desmin and CD34, but negative for EMA, cytokeratin, estrogen receptor, S-100 and myoglobin." (PMID 23217062, 2012). "With immunohistochemical stains, her tumor cells reacted positive for Bcl-2, CD34, and ki67 and negative for CD10, CD117, S100, and Desmin." (PMID 21819590, 2011). "We therefore concluded that the desmin-positive, vimentin-positive cells were typical pericytes, rather than VSMC, coating the tumor micro-vessels." (PMID 22141345, 2011). "With immunohistochemical stains, tumor cells reacted positive for CD34, Bcl-2, and ki67 and negative for CD10, CD117, S100, and Desmin." (PMID 21819590, 2011). "The tumor tissues showed a positive reaction for CD117, CD34 and vimentin, but not for desmin, PLAP, S-100, SM-actin, NF, GFAP, NSE, HMB-45, and SC-actin." (PMID 19500398, 2009). "Tumor cells showed diffuse strong immunoreactivity for vimentin and patchy strong staining for CD10; no reactivities were found for AE1/AE3, desmin, S-100, LCA, CD20, c-kit, and CD31." (PMID 21151512, 2009). "The tumor cells expressed CD99 (MIC2 gene), NSE and S100 protein, but were non-reactive to cytokeratins, epithelial membrane antigen, desmin, smooth muscle actin, chromogranin and leucocyte common antigen." (PMID 19830128, 2009). "Immunohistochemical analysis showed that the tumour cells expressed vimentin, but not smooth-muscle actin, CD34, or desmin." (PMID 18257933, 2008). "Immunohistochemical analysis showed that the tumour cells expressed vimentin, but not smooth-muscle actin (SMA), CD34, or desmin." (PMID 18257933, 2008). "Immunohistochemical studies on that tumor cells revealed positive staining for C-KIT (CD117), whereas CD34, antibodies against smooth-muscle actin (SMA), desmin, actine and S-100 protein were negative." (PMID 17958889, 2007). "The tumor cells were CD34-positive and negative for desmin, SMA, and S100." (PMID 40391055, 2025). "Tumour cells were strongly positive for CD204, Iba1 and desmin and negative for CD31 and SMA." (PMID 39814065, 2025).
tumor (continued). "IHC staining further confirmed tumor's smooth muscle and mesenchymal origins, with positive for vimentin, smooth muscle antibody (SMA), synapsin (Syn), actin, desmin, CD34 (vascular), while negative for and chromogranin A (CgA)." (PMID 39776317, 2025). "In this case, MyoD1 was negative and desmin and SMA were focally positive, which may represent a heterogeneous or incompletely differentiated state of the tumor cells." (PMID 40176092, 2025). "Desmin, SMA, S100, CD31, Caldesmon, TLE-1, WT-1 and SS18 were negative in the tumor." (PMID 40831926, 2025). "Tumour cells expressed DOG1, c-Kit, α-SMA and vimentin, and were negative to desmin and S-100." (PMID 40045318, 2025). "Tumour cells were negative for CD204, Iba1 and CD31, and strongly positive for desmin and SMA." (PMID 39814065, 2025). "Immunohistochemistry revealed that the tumor cells were positive for alpha-smooth muscle actin (αSMA) and negative for S100, CD34, desmin, anaplastic lymphoma kinase (ALK), anti-pan cytokeratin antibody (AE1/AE3), and EMA, and the Ki-67 labeling index was approximately 50%." (PMID 39816285, 2024). "The tumor cells were negative expression of epithelial markers, including PCK, EMA, CK8/18, CK20 and low molecular weight keratin (CAM5.2), as well as CgA, CD56, S100, HMB45, CD117, DOG1, CD99, WTI, Desmin and SMA." (PMID 38877473, 2024). "The tumor showed a positive reaction for S-100 and Ki-67, revealing its neural origin and high mitotic activity, a negative reaction for SMA and Desmin excluding the diagnosis of myofibrosarcoma; and a negative expression for p-53, ruling out the possibility of malignancy." (PMID 39713108, 2024). "Immunohistochemically, the tumor cells showed strong pancytoplasmic staining of the type III receptor tyrosine kinase (KIT) and the transmembrane protein discovered on GIST (DOG1) and negative staining for S100 and desmin." (PMID 37789344, 2023). "The tumour cells were diffusely positive for smooth muscle actin and GRM1 (in > 95% of the neoplastic cells), focally positive for CD34 and negative for S100 protein, desmin, cytokeratin AE1AE3 and ERG." (PMID 36810795, 2023). "Finally, the tumor was diagnosed as GCT on pathological assessment including immunohistochemical examination, as the tumor was positive for S-100 and negative for both KIT and Desmin." (PMID 34677732, 2022). "A wide range of immunohistochemical stainings were performed, such as CD68, SMA, desmin, EMA, mucin 4, SOX10, S100 and CD34, from which we could not deduce a specific differentiation line of the tumor cells." (PMID 35645621, 2022). "Furthermore, IHC analysis revealed that the Ki-67 labeling index (LI) was 30–40%, indicating highly proliferative tumor cells, and a large portion of tumor cells strongly expressed Pan-TRK, S-100, and CD34, while negative for vimentin, SOX10, and desmin." (PMID 35572973, 2022). "Cross striations may be appreciated and these tumours are positive for SMA, Desmin, and Myogenin, and are negative for S100P on immunohistochemical stains." (PMID 34514564, 2022). "Tumor cells of case No. 2 were positive for AE1/AE3, CK7, calretinin, D2-40, focal positive for WT-1, and negative for HMB45, Melan-A, Desmin, S100, Syn, CgA, CD31, and CD34." (PMID 34248850, 2021). "Three cell lines were excluded from further analyses as they exhibited a fibroblast-like phenotype in culture, expressed the fibroblast marker DESMIN and showed very low levels of expression of H-RAS, suggestive of fibroblast outgrowth of the culture rather than tumor cells." (PMID 33924486, 2021).
tumor (continued). "The postoperative pathology showed the tumor cells to be positive for chromogranin, synaptophysin, cytokeratin, CD56 (partial weak), negative for vimentin, CD117, DOG-1, CD34, S-100, SMA, desmin, and Ki-67 approximately 2%, which confirmed the diagnosis of d-NETs." (PMID 33578581, 2021). "We screened all cell lines by western blotting which revealed that 13 of 16 cell lines expressed high levels of H-RAS and lacked expression of the fibroblast marker DESMIN and muscle markers MYOGENIN and MYOD, consistent with these cell lines being tumor-derived." (PMID 33924486, 2021). "The morphology of this tumor resembles soft tissue myoepitheliomas, particularly those tumors with a myxoid pattern, but the neoplastic cells are negative for S100, GFAP and myogenic markers such as SMA, desmin." (PMID 31915021, 2020). "By immunohistochemistry, tumor cells demonstrated strong nuclear cyclin D1 expression and multifocal smooth muscle actin staining but were negative for MUC4, ERG, CD34, S-100 protein, desmin, STAT6, CD45, MDM2, CDK4, ALK, and ROS1." (PMID 32461620, 2020). "Tumour cells were negative for cytokeratin, EMA, and desmin." (PMID 33520482, 2020). "The tumor cells expressed immunoreactivity for vimentin, but not for S100, CD34, actin, or desmin." (PMID 32605652, 2020). "However, the tumor cells were negative for S-100 protein, SMA, desmin, myogenin, CD99, Fli-1, CD56, STAT6, CK and EMA." (PMID 32957984, 2020). "In our case, the tumor was positive for SMA and negative for desmin, S100, CR, and CD34." (PMID 32815307, 2020). "Immunohistochemistry (IHC) revealed that the tumor cells were positive for SMA, CD34, Vim, β-catenin, Fli-1, WT-1, CD117, Bcl-2, CyclinD1, CD31, CD99, INI-1 and Ki-67 (80%), and lacked EMA, CK, Myogenin, Desmin, CD68, and S-100." (PMID 31702654, 2019). "The tumor cells are negative for leukocyte common antigen, HMB-45, Melan-A, desmin, and myogenin." (PMID 28143624, 2017). "A pathologic examination showed neoplastic tissue composed of pleomorphic cells, while immunohistochemistry of the tumor cells was positive for vimentin and negative for Pan CK, EMA, S‐100, HMB‐45, SM‐actin, desmin, CD 31, CD 34, and CD 68, while 30% of tumor cells showed reactivity to Ki67." (PMID 28588856, 2017). "Tumor cells were negative for PAN-CK, desmin, S-100, melan-A, EMA, and CD10." (PMID 28270196, 2017). "However, on immunohistochemical analysis, the tumor was unexpectedly positive for MUC4, but negative for desmin, S100, smooth muscle actin, CD34, and CD117." (PMID 27247823, 2016). "Interestingly, perivascular PDGFR-β and desmin but not α-SMA status in normal and tumor tissue showed a significant correlation." (PMID 27248825, 2016). "The tumor cells show diffuse strong expression of Factor VIII, Fli-1, INI-1, vimentin, MDM2, and CDK4, local expression of CD31, AE1/AE3, EMA and P63, and no expression of CD34, S-100, actin-sm, desmin, MyoD1, and HMB45." (PMID 26315812, 2015). "The recurrent tumor demonstrated no further malignancy, but presented with a different immunophenotype, which was positive for FN (++), SMA (+) and CK (+) and negative for desmin (−)." (PMID 25624890, 2015). "Tumor cells from stomach were positive for SMA and collagen IV, and F8 was rare weakly positive, whereas they were negative for CD31, CD117, CK, dog-1, HMB45, desmin, and s-100." (PMID 25888833, 2015). "Immunohistochemical examination indicates that the tumor cells were diffusely positive for Factor VIII, Fli-1, CDK4, INI-1, MDM2, vimentin, focally positive for AE1/AE3, CD31 and negative for actin-sm, CD34, desmin, myoD1 and S-100." (PMID 26315812, 2015).
tumor (continued). "Immunohistochemical staining showed that the tumor cells were strongly positive for vimentin and CD99, focally positive for neuron specific enolase (NSE) and chromogranin A (CgA), and negative for cytokeratins, CD3, desmin, and leukocyte common antigen (LCA)." (PMID 23537038, 2013). "The tumor was diffusely positive for CD31, CD34, and ERG, with SMA-positive smooth muscle seen focally around vessel walls, and negative for AE1/AE3, S100 protein, desmin, and HHV8." (PMID 24383023, 2013). "The tumor was negative for D2-40, HHV8, desmin, AE1/AE3, MNF116, and CAM5.2." (PMID 24383023, 2013). "The tumor cells were negative for CD117, S100, CD34, a-SMA and desmin." (PMID 23902675, 2013). "In Prostatic stromal sarcoma (PSS) unlike the PES, immunohistochemically, the tumour cells are widely positive for vimentin, CD56, CD99 and focally positive for synaptophysin, CD10, progesterone receptor, desmin and CD34, but negative for EMA, cytokeratin, estrogen receptor, S-100 and myoglobin." (PMID 23886403, 2013). "Immunohistochemistry the tumor was positive for vimentin, smooth muscle actin and Ki-67; focal positivity with AE1-AE3 CK, CK5 and high molecular weight cytokeratin and negative for EMA, CD34, desmin, myosin, CroA, synaptophysin and S100." (PMID 23886403, 2013). "The tumor cells were negative for α-SMA, S-100, desmin, CD34 and CD117." (PMID 23902675, 2013). "The tumour cells showed diffuse immunopositivity for SMA (contractile protein actin) and vimentin (a mesenchymal cell intermediate filament) and negative for desmin (Smooth muscle antigen) and S-100 (nervous tissue antigen) which has been consistently used to spot a myofibroblastic lineage." (PMID 22966474, 2012). "Tumor cells stained negative for CD10, CD20, CD79a, CD34, CD56, CD117, TdT, Desmin, and EMA." (PMID 22497840, 2012). "Immunohistochemical studies were helpful in making a diagnosis, and several reports have suggested that spindle and epithelioid tumor cells show strong positive staining for SMA, desmin, and vimentin, and the absence of staining for cytokeratin as well as S-100 protein." (PMID 22248347, 2012). "However, the tumor cells do not express S-100 protein, desmin, or myoglobin, but do express AACT and CD68; 3) In leiomyosarcoma, the pattern of growth is predominantly fascicular, with the tumor bundles intersecting each other at wide angles." (PMID 22515616, 2012). "The tumor cells of the five cases were negative for SMA, desmin, CD117 and CD34." (PMID 22862905, 2012). "The tumor cells were positive for CD99 and negative for chromogranin A, keratin and desmin." (PMID 21494688, 2011). "The tumor cells were positive for CD34, and negative for α-smooth muscle actin and desmin." (PMID 21143833, 2010). "Interestingly, although each tumor type utilized the MSC as a TAF, as confirmed by the presence of α-SMA, desmin, Tn-C and TSP1, similarities between the IHC staining patterns do not exist across tumor types." (PMID 19352430, 2009). "The tumor exhibits positivity for Vimentin, PR, and SMA, with negativity for PanCk, S100, Desmin, PSA, CK5/6, BCL2, MDM2, and Melan A. Additionally, the Ki-67 proliferation index is approximately 25 %, and CD34 highlights only the vascular walls without tumor cell positivity." (PMID 40686513, 2025). "Moreover, by immunohistochemistry (IHC), the tumor showed diffuse reactivity for vascular markers, including ERG, CD31, CD34, and D2-40, as well as for TFE3, while being negative for MUC4, CAMTA1, smooth-muscle actin, desmin, S100 and keratins." (PMID 40879254, 2025). "Similarly, our case showed focal positivity for both CD34 and S100, while additional immunoreactivity may be present but is less specific for this type of neoplasm (e.g., WT1, CD10, desmin, and smooth muscle actin; not shown)." (PMID 39582973, 2024).
tumor (continued). "Additionally, the tumor was negative for most immunohistochemical markers (CKAE1/AE3, p63, CD23, CD21, MUC4, NUT, CDK4, Pan-TRK, STAT6, SS18, MDM2, Desmin, S100, ERG, TLE1, Fli) and showed only weak and most probably unspecific expression of CD99, CD56, and CD34." (PMID 39519042, 2024). "Most notably, the tumor was found to be negative for Brachyury, CD68, SRY-box transcription factor 10 (SOX10), HMB45, glial fibrillary acidic protein, oligodendrocyte transcription factor 2, anaplastic lymphoma kinase, desmin, CD117, synaptophysin, and neurofilament." (PMID 37598295, 2023). "The tumor may show variable and focal expression of SMA, S100, CD34, and rarely desmin (or none)." (PMID 35565289, 2022). "Immunohistochemically, the staining results of tumor cells in the small intestine and kidney were consistent; the tumor cells were positive for CD3, CD56, granzyme B, TIA-1, and perforin, while negative for CD4, CD8, CD5, Desmin, CD34, CKpan, CD20, CD30, SMA, CD79ɑ, and PAX8." (PMID 36199094, 2022). "Thirteen additional patients were screened but excluded because no tumor sample was available for analysis (n = 6) or because the diagnosis of RMS has not been confirmed by histological review (with different morphologic appearance and/or desmin and myogenin negative—n = 7)." (PMID 32087612, 2020). "However, negative for myogenic markers including desmin and myogenin, can readily exclude the possibility of embryonic RMS, and absence of expression of S100 protein and SOX10 together with retained expression of H3K27me3 disagree with a malignant triton tumor." (PMID 35125107, 2022). "Indeed, while these tumours showed high levels of H-RAS expression in comparison to adjacent normal tissue and were immunoreactive for the common mesenchymal marker VIMENTIN, the tumour cells did not stain for lineage markers including CD31, vWF, DESMIN, SMA, MYOD1 or MYOGENIN (last column)." (PMID 29731980, 2018).